CD4 (CD4 molecule)
Diseases named in the same sentence as CD4 in open-access papers (continued):
Sharing a sentence is not in itself a finding about the gene and the disease.
tumor (continued). "Importantly, despite the CD137 staining only minimally improving the detection of tumor-specific reactive CD4+ TILs, the assay effectively detected both CD8+ and CD4+ tumor-reactive TILs simultaneously." (PMID 34707600, 2021). "To further characterize the mechanisms contributing to the SpatialScore, we used CODEX and RNA-seq datasets to explore whether the closer proximity of PD-1+ CD4+ T cells and tumor cells in responders reflected enhanced T cell effector function." (PMID 34795254, 2021). "Different types of CD4+ T cells in tumor microenvironments may also contribute to the tumor progression." (PMID 33946835, 2021). "Those inhibitory receptors could combine with corresponding inhibitory ligands of DCs and tumor cells, induce the disability of CD4+ TILs or suppress the cytotoxic reaction of CD8+ TILs, which finally mediated the immune tolerance to the tumor." (PMID 34566989, 2021). "When compared to the circulating blood of HCC patients, they found that terminally differentiated effectors (TEFF) strongly reduced and exhausted in both peritumor and central tumor, indicating that CD4+ TILs were selectively recruited into the tumor to escape the immune system." (PMID 34566989, 2021). "Furthermore, T cells when incubated with human mutant KRAS tumor-derived exosomes induced increased secretion of IL-10 from naïve CD4 T cells and increased the switch of naïve CD4 T cells into FoxP3+ phenotype, both of which lead to an immunosuppressive TME." (PMID 34831378, 2021). "The increased CD8+ and CD4+ T cells proved that MnP@Lip could contribute to recruiting immune cells to tumor microenvironment and boosting adaptive immune response." (PMID 34895243, 2021). "To confirm the reduced abundance of CXCL13+CD4+ T cells in EGFR-MT compared with EGFR-WT tumor, inferred from the single-cell transcriptome analysis, we performed the multiplexed immunofluorescence (IF) staining in archival tissue specimens of the same samples." (PMID 34663810, 2021). "Notably, the tumor growth suppression in the Cd4-Cre+Lsd1f/f mice began to appear only when growth in wildtype mice had already entered the acceleration stage." (PMID 34819502, 2021). "Collectively, the present results confirmed that knockdown of CRNDE-h in CD4+ T cells could inhibit CRC tumor growth in mice." (PMID 33495437, 2021). "It has been reported before that CIITA-transfected tumor cells gained ability to prime in vivo naïve CD4+ cells, and thus, they may serve as APCs." (PMID 33592498, 2021). "We speculate that the increased RNA and protein expression of CXCL13 in responder tumor cells following pembrolizumab therapy is advantageous in localizing effector PD-1+ CD4+ T cells within the TME." (PMID 34795254, 2021). "The proportion of Tregs in splenic CD4+ T cells from cryo-thermal treated mice was decreased compared with that in the tumor-bearing control, but TNF-α supplementation after cryo-thermal therapy increased the proportion of Tregs compared to cryo-thermal therapy alone." (PMID 34576115, 2021). "In addition to increased tumor growth control, immunological analysis of the treated tumors revealed significant infiltration of CD4+, CD8+ as well as Trp2-specific CD8+ T cells into the TME of the PeptiBAC-Trp2+ICI-treated mice." (PMID 34266884, 2021). "Whether ZHX2 could remodel the tumor microenvironment in a TGF‐β dependent pathway in CD4+ T cells requires further exploration." (PMID 33837660, 2021). "This could be because CD4+TILs were already in a hostile immunosuppressive tumor microenvironment and attained terminal differentiation, limiting their ex vivo plasticity." (PMID 33918403, 2021). "In addition, we have clearly shown that tumor regression is driven by CD4+ T cells, since the peripheral depletion of this compartment completely abolishes the anti-tumoral effects of CPIs, while the efficacy was maintained despite CD8+ T cell depletion." (PMID 34072037, 2021).
tumor (continued). "Moreover, IRF1 expression in tumor cells was also reported to be critical for the immune response to adoptive T cell therapy, as well as macrophage infiltration and memory CD4+ T cell activation." (PMID 34277600, 2021). "PD-1 blockade restored helper activity of exhausted PD-1high, CD39+ tumor infiltrating CD4 T cells." (PMID 34064410, 2021). "By analyzing immune cell constituents, we found PD-L1 blockade alone could not effectively increase the infiltration of adaptive immune cells (CD8+ and CD4+ T cells) or their anti-tumor functions comparing with those of control ones." (PMID 34815793, 2021). "Importantly, we observed that in lung tumor-infiltrating CD4+ T cells from CD4/ALK4-KO mice, Tox and Tox2 demonstrated significantly enriched binding on the -23 kb enhancer sequence of Pdcd1, compared to their WT counterparts." (PMID 34548096, 2021). "Thus, modification of antigen-encoding peptides with C16:0 provides a multi-pronged improvement of antigen-specific CTL responses, CD4+ T cell activity, and recognition of tumor cells, affecting both the induction and effector phase of anti-cancer immunity." (PMID 34141869, 2021). "Thus, CD25-targeted NIR-PIT was developed to selectively deplete CD4+CD25+Foxp3+ Tregs in tumor beds to induce the activation of antitumor effector cells." (PMID 34064074, 2021). "Moreover, although a recent study reported that cancer cells produced TGF-β1 in tumor supernatants and when CD4+ T cells were cultured in tumor supernatants, FOXP3+ Tregs generation was promoted." (PMID 34026621, 2021). "We initially searched for markers associated with tumor-antigen recognition that could be used in both main subpopulations of TILs (CD8+ and CD4+ TILs)." (PMID 34707600, 2021). "A similar distribution was observed for both B and CD4+ T cells, suggesting that these cells could be interacting in the tumor site." (PMID 34868006, 2021). "Finally, we discussed how to manipulate tumor reactive CD4+ Th responses by epigenetic drugs to improve anticancer immunotherapy." (PMID 34262562, 2021). "We designed a method, called TICPE, to estimate the proportions of eight important tumor-infiltrating immune cells (B cells, CD4+ T cells, CD8+ T cells, dendritic cells (DC), monocytes, macrophages, natural killer (NK) cells, and neutrophils) in a specify type of cancer." (PMID 34054849, 2021). "Immune responses seem to be mediated by CD8+ T lymphocytes within the tumor, although additional cell types (such as CD4+ T cells) may also contribute to immune surveillance." (PMID 34445631, 2021). "Tumor-specific CD4+ and CD8+ T cell effector responses have been observed in the BM of MGUS." (PMID 33717170, 2021). "We demonstrated that the level of CD4+ GzmB+ T cells located in the center of tumor could provide great prognostic value for pMMR CRC patients." (PMID 34631551, 2021). "However, anti-IFN-γ significantly impaired the infiltration of CD8+CXCR3+ and CD4+CXCR3+ T cell subsets into the tumour mass." (PMID 33925140, 2021). "Moreover, expression of microglial MHC II is reduced in HGGs indicating diminished antigen-presenting ability of GAMs, which further hindered CD4+ T-cell activation at tumor site." (PMID 34715891, 2021). "However, the last 5 years have seen many reports recognising the critical role of CD4+ T cells in driving anti-tumour immunity and in supporting anti-tumour CD8+ T cell responses." (PMID 32457487, 2021). "The combinative form did not cause high-dose 4-1BB-related toxicity with CD4+T cell reduction, but it notably produced antigen-specific tumor IFN-γ which secreted effector CD8+ cytotoxic T cells." (PMID 34267616, 2021). "Interestingly, in tumor-bearing mice, CD4+ CD19-CAR T-cells exhibited higher anti-CD19 activity and outperformed CD8+ CAR T-cells especially in the context of higher tumor burden, suggesting that CD4+ CAR T-cells are less prone to exhaustion." (PMID 34367185, 2021).
tumor (continued). "Additionally, these tumor Tregs suppressed the proliferation and effector function of tumor-derived CD4+ responder population using both cell contact and cytokine secretion." (PMID 33996630, 2021). "In addition, the level of serum CD4 is related to the infiltration of CD4+T cells in the tumor microenvironment." (PMID 34258299, 2021). "A recent study showed that LMP1 signaling in B cells led to an overexpression of tumour associated antigens presented on MHC-I and II, and the upregulation of costimulatory ligands CD70 and OX40L, thereby inducing potent cytotoxic CD4+ and CD8+ T-cell responses." (PMID 34956172, 2021). "Since tumor infiltrating CD4+ T cells had distinct epigenetic signature compared to the CD4+ T cells from the blood in the same patient, we hypothesized that TME induces these changes in tumor infiltrating T-cells." (PMID 34012510, 2021). "Independent of treatment, residual CAR-T cells in the tumor at the time of necropsy were exclusively CD4+ underlying the notion that in this immune-deficient model, CD4+ T cells benefit from an intrinsic survival advantage." (PMID 34743703, 2021). "For instance, a recent study revealed that resting memory CD4 T cells was one of the most abundant tumour-infiltrating immune cells in GC samples; in addition, the infiltration levels of activated memory CD4 T cells was positively correlated with a favourable prognosis for GC patients." (PMID 33602220, 2021). "Furthermore, Western blot analysis of protein lysates prepared from thymic tumours obtained from the CD4/NPM-ALK transgenic mouse line also express BRG1 albeit at a lower level than that observed in ALK+ ALCL cell lines." (PMID 35008316, 2021). "The biological process analysis showed that the genes co-expressed with KEGG were enriched in the regulation of DNA binding, CD4-positive T-cell activation, protein transport along the microtubule, cell growth, and T-cell differentiation, which were closely related to tumor cell proliferation." (PMID 33540574, 2021). "Overexpression of cyclin G2 generated immune-favorable TME, evident by the reduced proportion of Tregs and elevated tumor-infiltrating IFN-γ + CD4 + and IFN-γ + CD8 + T cells, as well as low levels of immunosuppressive cytokines and elevated cytotoxic cytokines." (PMID 34452627, 2021). "CD4 T cells can control tumor growth by acting on tumor microenvironment." (PMID 34201655, 2021). "Second, insufficient CD8+ T cells and abundant PD1+ CD4+ T cells that react to invading tumour cells might contribute to regional immune suppression in the liver metastatic niche." (PMID 34021647, 2021). "IL21R was highly expressed on a broad range of tumor-infiltrating immune cells, including CD4+ Tconv cells, T regulatory cells (Tregs), CD8+ T cells, B cells, NK cells, macrophages, monocytes, and dendritic cells (DCs) but minimally expressed in neutrophils and mast cells." (PMID 34869384, 2021). "Importantly, the BCSP subset has a history of CD4 expression and a marked wrist location tropism, explaining why the wrist is the main site of tumor development." (PMID 34625577, 2021). "In addition, the expression level of CD8+ T cell-derived Exo-PD-1 was higher than Exo-PD-1 from CD4+ T cells, yet generally speaking, tumor-infiltrating CD8+ and CD4+ T lymphocytes both contributed to the production of Exo-PD-1 within tumor microenvironment." (PMID 34172932, 2021). "Specifically, it was observed that Olaparib increased intratumoral CD4+ and CD8+ cells, decreased the production of inhibitory receptors, increased the recruitment and activity of tumor associated dendritic cells, therefore providing a robust immune activation both innate and adaptive." (PMID 34195090, 2021). "Moreover, pDCs can effectively promote the differentiation of naive CD4+ T cells into Tregs, thereby facilitating tumor immune escape." (PMID 34737750, 2021).
tumor (continued). "In view of this limitation, using a murine breast tumor model, we tested a hypothesis that ex vivo high salt activation of CD4+T cells from tumor bearing mice followed by the adoptive transfer of these T cells would exert effective anti-tumor responses." (PMID 33918403, 2021). "A parallel series of experiments in the same study, using OTII+ CD4 T cells adoptively transferred into B16OVA tumor-bearing mice, indicated that the VISTA blockade decreased the percentage of induced, CD4+ FoxP3+ Treg cells amongst TILs, and in the draining lymph node." (PMID 34282763, 2021). "Furthermore, high expression level of IGF-1 and IGF-1R were closely connected with high degrees of tumor infiltrates, including CD4+ T cell, dendritic cells, and macrophages." (PMID 34804946, 2021). "Additionally, effector and memory Th1 CD4+ T cells are pivotal in effective anti-tumor immunity and that CD4+ T cells induce more durable immune responses than CD8+ T cells." (PMID 34898475, 2021). "CD4 T cell frequency was highly increased upon combination treatment in TC-1 tumors, while it remained unchanged in STINGa monotherapy, highlighting again that vaccination is required for tumor infiltration in this tumor model." (PMID 34276686, 2021). "In one study, a higher proportion of CD8+ Tc (median 51.6%) was observed in tumor-infiltrating lymphocytes relative to peripheral blood leukocytes (23.9%), while ascites samples contained similar proportions of CD4+ Th and CD8+ Tc (46.5% and 44.5%, respectively)." (PMID 34503128, 2021). "CD4 T cells have been recognized as crucial for effective immunotherapy, mainly due to their capacity to enhance cytotoxic T cell responses and re-program the tumor microenvironment." (PMID 34046035, 2021). "We postulate that memory CD4 T cells are also key mediators of systemic immunity in this model, protecting mice from intracerebral rechallenge by secreting proinflammatory cytokines and activating NK cells at the new tumor site." (PMID 34083417, 2021). "The infiltration of CD4+ T cells and NK cells in the tumor was also detected." (PMID 34158852, 2021). "Besides the traditional helper and regulatory CD4 T cell classification, recent evidence demonstrated the existence of tumor-specific CD4 T cells with cytolytic capacity that can directly eliminate tumor cells." (PMID 34064410, 2021). "Thus, activation of STAT3 in CD4+ T cells generates an inflammatory environment around the OvCa, which promotes tumor growth by stimulating angiogenesis and suppressing anti-tumor response." (PMID 34248988, 2021). "Depletion of tumor-associated macrophages (TAMs) in pancreatic cancer could also reprogram the epigenetic profile of tumor infiltrating CD8+ and CD4+ T cells." (PMID 34262562, 2021). "Similar results were obtained by comparing CD4+ T cells in the adjacent normal and tumor tissues." (PMID 33513276, 2021). "Likewise, IFN-γ production of tumor-infiltrating CD4+ T cells was significantly increased in i.t. compared to i.v. artLCMV-TRP2-treated mice." (PMID 34354077, 2021). "During the onset of the tumor, both CD4+ and CD8+ cells are enriched at the tumor site." (PMID 34616914, 2021). "Self-reactive anti-tumour CD4+ T cells—the next frontier in cancer immunotherapy?" (PMID 32457487, 2021). "In 2011, Yasuda and colleagues reported a histochemical assessment of advanced rectal cancers showing that higher densities of CD8+ as well as CD4+ TILs in pre-treatment biopsies were correlated to a good tumour response after chemoradiotherapy in terms of reduced tumour size and histological grade." (PMID 34321074, 2021). "The CD4+ T cells could eliminate tumor cells directly through cytolytic activity.Moreover, the activated CD4+ T cells are able to reshape the tumor immune microenvironment and facilitate tumor clearance." (PMID 34880875, 2021). "Within the TME, Treg cells consist of a large proportion of human tumor CD4+ infiltrates." (PMID 34804061, 2021).
tumor (continued). "However, after cryo-thermal therapy, the expression level of the CTL cytokine perforin in CD4+ T cells was significantly upregulated compared with that in the tumor-bearing control and RFA groups." (PMID 34576115, 2021). "Regarding the fundamental question of how cytotoxic CD4+ T cells kill human tumor target cells, the prior data from cytotoxic CD4+ T cells in murine models points to contact-dependent cytotoxicity in a granzyme- and MHC class II-dependent fashion, where the action of IFN-γ is dispensable." (PMID 34910940, 2021). "Our study indicates that the reduction of CD4 cells in tumor tissues with low expression of PBRM1 may explain the compromised efficacy of anti-PD-1 immunotherapy in patients with PBRM1 mutated ccRCC." (PMID 34447697, 2021). "CD4+CD25++Tregs in advanced (stage III-IV) HCC patients is significantly increased compared to early (stage I-II) HCC patients, implying that the presence of CD4+CD25++Tregs is closely related to tumour progression and enhances the invasiveness and metastasis of HCC." (PMID 33995362, 2021). "In addition, CD8+ T cells and CD4+ T cells are widely acknowledged as the main components of tumor-infiltrating lymphocytes (TLSs), and participate in anti-tumor immunity." (PMID 35198564, 2021). "We concluded that M1M2d, a tumoricidal-regulatory macrophage, could potentially eliminate tumor cells due to the secretion of cytotoxic cytokines and IL-12, the latest helps to differentiate CD4+ T cells." (PMID 34177892, 2021). "Among them, CD4+Th2 cells promote tumor growth, while CTLs inhibit tumorigenesis." (PMID 34497832, 2021). "This would suggest that inhibition of HDAC1 and HDAC11 might be attempted to promote CD4+ T cell function at the tumor site." (PMID 33859645, 2021). "These vaccines induced potent antigen-specific CD8+ and CD4+ T cell responses that had antitumor activity in mice that was enhanced by combining autologous T cells modified with tumor antigens and additional adjuvant signals (Tvax) with immune checkpoint blockade (ICB) and other immunomodulators." (PMID 34396986, 2021). "Indeed, studies have implicated the NLRP3-mediated release of IL-1β in the induction of the IL-22 cytokine by CD4+ T cells, a process observed to support tumor cell proliferation and growth." (PMID 34638239, 2021). "Neoepitope-specific CD4+ T cells of the TH1 subtype are involved in anti-tumor responses." (PMID 35097027, 2021). "Therefore, until proven otherwise, we cannot exclude that ACT therapy would work for patients with tumours that predominantly contain CD4+ TILs." (PMID 34503115, 2021). "It is likely that in the protected mice immunized with the anti-DEC-205:16E5 conjugate, the CD8+ T cells were functioning efficiently as effector cells, due to the effective T cell help provided by the 16E5-specific CD4+ T cells, which allowed them to eliminate the tumor cells." (PMID 33717073, 2021). "It is expressed on tumor infiltrating lymphocytes (CD4+ and CD8+ T cells), Treg, NKT cells." (PMID 33805268, 2021). "Gene expression analysis of the tumor further supported the phenotypic analysis in both PD-1cKO- and PD-1 Ab-treated mice and showed an upregulation of pathways related to CD4 and CD8 T-cell activation, enhanced signaling through costimulatory molecules and IFNγ, and non-T-cell processes." (PMID 34912335, 2021). "The PR-SA comparison data revealed that clusters 0, 2, 3, 4, 6, and 9 might be tumor cells derived from liver bud hepatic cells, and cluster seven is an immune cell cluster based on exhausted CD4+ T cells." (PMID 34421602, 2021). "Regulatory T cells (Tregs) represents the majority of CD4+ tumor infiltrating Puro+ cells." (PMID 34787568, 2021). "Similarly, the number of tumor-infiltrating CD4+, CD8+, and NK (natural killer) cells able to produce IFN-γ was significantly higher in mice treated with CM1315, suggesting that Treg inhibition improved the antitumor immune response." (PMID 33671179, 2021).